ST6GALNAC2 (ST6 N-acetylgalactosaminide alpha-2,6-sialyltransferase 2)
Description:
Catalyzes the transfer of N-acetylneuraminyl groups onto glycan chains in glycoproteins. Conjugates sialic acid with an alpha-2-6 linkage to N-acetylgalactosamine (GalNAc) glycan chains linked to serine or threonine in glycoproteins. Sialylates alphaGalNAc- and Galbeta1->3GalNAc-O-Ser/Thr epitopes also known as Tn and T antigens.
Synonyms: SIAT7B; SIATL1; STHM; ST6GalNAII; SAITL1; SIAT7
Tractability: Small molecule: a structure with a bound ligand is known. Antibody: UniProt predicts a signal peptide or a membrane-spanning region.
Gene: Protein-coding gene on chromosome 17 (76,565,377 to 76,586,956, reverse strand). Ensembl gene ENSG00000070731.
Subcellular location: Golgi apparatus membrane
Pathways (Reactome):
Disease: Maturation of protein 3a; Maturation of spike protein
Metabolism of proteins: Sialic acid metabolism; Termination of O-glycan biosynthesis
Gene Ontology:
Molecular function: alpha-N-acetylgalactosaminide alpha-2,6-sialyltransferase activity; sialyltransferase activity
Biological process: glycoprotein biosynthetic process; protein O-linked glycosylation; protein sialylation; protein O-linked glycosylation via N-acetyl-galactosamine; viral protein processing; carbohydrate derivative biosynthetic process
Cellular component: Golgi membrane
Genetic constraint (gnomAD): Loss-of-function variants: 36 observed, 31.28 expected, observed/expected ratio (o/e) 1.15, 90% interval 0.88 to 1.52. The upper end of that interval is the gene's LOEUF score, 1.52, which puts it in group 6 of 6, group 1 being the genes least tolerant of losing a copy. Missense variants: 501 observed, 468.91 expected, observed/expected ratio (o/e) 1.07, 90% interval 0.99 to 1.15. Synonymous variants: 233 observed, 202.07 expected, observed/expected ratio (o/e) 1.15, 90% interval 1.03 to 1.28.
Homologues: Orthologues: chimpanzee ST6GALNAC2 (95% identical), macaque ST6GALNAC2 (81% identical), pig ST6GALNAC2 (81% identical), mouse St6galnac2 (75% identical), guinea pig ST6GALNAC2 (75% identical), dog ST6GALNAC2 (74% identical), rat St6galnac2 (72% identical), rabbit ST6GALNAC2 (71% identical), tropical clawed frog st6galnac2 (55% identical). Paralogues in human: ST6GALNAC1 (38% identical), ST3GAL3 (24% identical), ST3GAL1 (22% identical), ST3GAL2 (21% identical), ST3GAL4 (20% identical), ST3GAL6 (19% identical), ST6GAL2 (19% identical), ST3GAL5 (19% identical), ST6GAL1 (18% identical), ST6GALNAC5 (17% identical), ST6GALNAC4 (17% identical), ST6GALNAC3 (14% identical), and 2 more.
Diseases named in the same sentence as ST6GALNAC2 in open-access papers:
ST6GALNAC2 is named in the same sentence as 15 diseases in open-access papers, as found by Europe PMC text mining. Sharing a sentence is not in itself a finding about the gene and the disease. The quoted sentences say what the papers report.
breast carcinoma (8 papers, 2015 to 2025). "Although sialyl-Tn is associated with a poor outcome for breast cancer, ST6GalNAc2 was identified as a metastasis suppressor of breast cancer by in vivo RNA interference (RNAi) screen combined with next-generation sequencing." (PMID 36497322, 2022). "ST6GALNAC2 is known as a metastasis suppressor in breast cancer and a low expression of it, as we observed in glycated BEN-MEN-1 cells, is associated with a bad prognosis." (PMID 34943806, 2021). "Furthermore, ST6GALNAC2 has been shown to promote the invasive capabilities of breast carcinoma cells, potentially through activation of the PI3K/Akt/NF-κB signaling pathway." (PMID 40718829, 2025). "However, the role of ST6GalNac2 in cancer appears not to be unequivocally detrimental as Murugaesu and colleagues identified ST6GalNAc2 as a novel metastasis suppressor in mouse and human breast cancer models." (PMID 34975914, 2021).
COVID-19 (2 papers, 2023 to 2024). A disease caused by infection with severe acute respiratory syndrome coronavirus 2. "The expression of the α−2,3 sialyltransferase ST3GAL4 and the O-glycan α−2,6 sialyltransferase ST6GALNAC2 were significantly elevated in the severe COVID-19 cohort." (PMID 37398192, 2023).
lymph node metastases (2 papers, 2015 to 2023). "In addition, the study found that elevated expression of ST6GalNAc2 was associated with histological grade, clinical stage, and lymph node metastasis of FTC." (PMID 38003522, 2023).
atopic dermatitis (1 paper, 2024). "In the combined dataset, the expression of galactose-deficient IgA1-associated genes (including GALNT2, GALNT12, C1GALT1, C1GALT1C1 and ST6GALNAC2) were compared between atopic dermatitis patients and healthy controls." (PMID 39119579, 2024).
benign meningioma (1 paper, 2021). A grade I, slowly growing meningioma. "In the benign meningioma cell line, glycation led to differences in expression of sialyltransferases (ST3GAL1/2/3/5/6, ST6GAL1/2, ST6GALNAC2/6, and ST8SIA1/2), which are known to play a role in tumor progression." (PMID 34943806, 2021).
diabetes (1 paper, 2015). "In the type II enzyme family of α-2, 6 sialyltransferases, ST6gal1, St6galnac2, and 3 are highly expressed in kidney IM but they did not change in diabetes." (PMID 26483702, 2015).
lung carcinoma (1 paper, 2025). "ST6GALNAC2 expression pattern and its potential implications in human lung cancer tissues remain unexplored in prior research." (PMID 40718829, 2025).
melanoma (1 paper, 2019). A malignant, usually aggressive tumor composed of atypical, neoplastic melanocytes. "With regard to the genes specifically up-regulated in the MCSP CTC fraction, the majority have been involved in metastasis (LOXL4, ST6GALNAC2, PYGL), tumour growth (PLK2, CYSTM1, GLUL), and/or melanoma biology (SEC31A, WIPI1, SKP1)." (PMID 30769764, 2019).
prostate carcinoma (1 paper, 2018). A carcinoma that arises from epithelial cells of the prostate gland. "The hub genes in the “PRAD: magenta” module were identified to be abnormally expressed in prostate cancers, such as LAMB3 and ST6GALNAC2." (PMID 30181502, 2018).
thyroid cancer (1 paper, 2023). "Studies on the involvement of sialyltransferases in thyroid cancer mainly focused on N-acetylgalactosamine-specific α2,6-sialyltransferase 2 (ST6GalNAc2)." (PMID 38003522, 2023).
tumor (9 papers, 2016 to 2024). "On the other hand, HBE displayed higher levels of expression of the sialyltransferases ST6GALNAC1 and ST6GALNAC2, which are responsible for biosynthesis of the tumor-associated antigens sialyl-Tn and sialyl-6-T." (PMID 33919332, 2021). "The putative ligand of Siglec-15, Sialyl-Tn (STn), is associated with tumour progression and is synthesised by the sialyltransferases ST6GALNAC1 and ST6GALNAC2." (PMID 39348343, 2024). "Both ST8SIA1 and ST6GALNAC2 belong to the sialyltransferase (ST) family of enzymes, which promote tumour growth and metastasis." (PMID 33865381, 2021). "A xenograft of FTC-238 cells with silenced ST6GalNAc2 showed lower tumor volume in mice, as compared with the control FTC-238 xenograft." (PMID 30227620, 2018). "Previous studies have highlighted miR-182 and miR-135b were shown to modulate the expression of ST6GALNAC2 via the PI3K/AKT pathway, promoting chemoresistance and tumour invasiveness." (PMID 39348343, 2024). "The expression of miR-182 and miR-135b in tumour tissues and cells is higher than that in normal tissues, and the angiogenesis of CRC is promoted by direct targeting of ST6GALNAC2 to activate the PI3K/AKT pathway." (PMID 33865381, 2021). "Overexpression of ST6GalNAc2 in the FTC-133 non-invasive cell line enhanced its invasive ability and increased the tumor volume in xenograft mouse." (PMID 30227620, 2018).
cancer (6 papers, 2014 to 2024). A tumor composed of atypical neoplastic, often pleomorphic cells that invade other tissues. "ST6GalNac2, known to have a role in cancer, also appears to be upregulated in the presence of overexpressed SIRT6 in HUVEC-SIRT6 samples." (PMID 36982232, 2023). "ST6GalNAc2 has been proposed to enhance invasive properties of cancer cell lines via PI3K/Akt pathway signaling." (PMID 34975914, 2021). "Similarly, ST6GALNAC2 was shown to be co-expressed with and function alongside AHSG, an oncogene that is commonly associated with metabolic processes that have shown abnormal expression in multiple cancer types." (PMID 39348343, 2024). "Similarly, ST6GALNAC2 participates in STn antigen generation to a lesser extent and demonstrates high expression in CRC, and exhibits advanced cancer progression in follicular thyroid carcinomas (FTC)." (PMID 39348343, 2024). "It remains to be determined whether elevated expression of ST6GALNAC2 may lead to abnormal localization of the enzyme in Golgi apparatus, as described for ST6GALNAC1 overexpressed in cancer cells producing glycoproteins with sialylated GalNAc." (PMID 24398680, 2014).
infection (1 paper, 2020). The state of being infected such as from the introduction of a foreign agent such as serum, vaccine, antigenic substance or organism. "We observed that these genes did not change expression in non-CF ALI cultures upon infection with RV; ST8SIA4 (3.6-fold, p = 0.14); ST6GALNAC2 (−1.3-fold, p = 0.09); MAN1A1 (5.4-fold; p = 0.08); B3GNT8 (1-fold, p = 0.28)." (PMID 32765492, 2020).
ST6GALNAC2 also shares sentences with these, for which no sentence is quoted: colorectal carcinoma (1 paper); phyllodes tumors of the breast (1).